SIRT1 (sirtuin 1)
Diseases named in the same sentence as SIRT1 in open-access papers (continued):
Sharing a sentence is not in itself a finding about the gene and the disease.
type 2 diabetes (continued). "Thus, we want to examine the effects of AST supplementation on the expression of SIRT1, AMPK activity, and fatty acid levels in individuals with type 2 diabetes and their connection." (PMID 37534224, 2023). "Additionally, the dysregulation of metabolic pathways involving SIRT1 may lead to type 2 diabetes (T2D), which is characterized by high glucose concentrations caused by insulin resistance." (PMID 35277012, 2022). "Moreover, in accordance with the cumulative evidence, SIRT1 and SIRT6 repress pancreatic β cell dysfunction, attenuating the development of type II diabetes." (PMID 36552655, 2022). "A study was conducted on 44 obese, postmenopausal females who had or did not have type 2 diabetes to investigate the effects of fenofibrate, a medication to lower cholesterol, alone or in conjunction with pioglitazone on SIRT1 levels." (PMID 36225477, 2022). "High-fat diet-fed streptozotocin-induced type 2 diabetic rats were exposed to adiponectin with or without administration of the SIRT1 inhibitor EX527 following lung transplantation." (PMID 34602075, 2021). "Therefore, further researches are needed to have a broader vision about cinnamon intake on plasma level of NF-kB, SIRT1 and systemic inflammation factors including hs-CRP, IL-6 and TNF-α in type 2 diabetes patients." (PMID 31901246, 2020). "Moreover, administration of NMN, in a murine model of type 2 diabetes (T2D), restores HFD-induced p65 subunit acetylation of NF-κB and the inflammatory gene response, improving also hepatic insulin sensitivity, via SIRT1 activation." (PMID 32485811, 2020). "Recent research studies have substantiated that acetyl-histone 3 might be a key analgesic target for SIRT1 in neuropathic pain induced by CCI and type 2 diabetes." (PMID 32922581, 2020). "In pancreatic islet cells from type 2 diabetic patients, miR-124a was highly expressed, and its silencing in MIN-6 cells resulted in increased expression of genes involved in insulin secretion, such as Mtpn, Foxa2, Sirt1, and NeuroD1." (PMID 30974824, 2019). "The findings reveal that SIRT1/FOXO1 may involve in the initiation and development of DN in Han Chinese patients with type 2 diabetes." (PMID 28860538, 2017). "The present study has provided evidence that suggests treatment with the oral SIRT1 activator, SRT2104, may lead to an improvement in measures of arterial compliance in otherwise healthy cigarette smokers and people with type 2 diabetes." (PMID 27239324, 2016). "We aimed to analyse Sirtuin 1 (SIRT1) and Vitamin D receptor (VDR) expression levels in the peripheral blood of patients with type 2 diabetes (T2D), characterized for the presence of diabetic neuropathy (DN), and to evaluate possible genetic factors that could influence the VDR expression levels." (PMID 39976627, 2025). "Compared with the healthy group, the expression of SIRT1 mRNA in type 2 diabetes without depression group and type 2 diabetes comorbid depression group decreased, which was consistent with the expected results, indicating that SIRT1 played a role in type 2 diabetes comorbid depression." (PMID 39612426, 2024). "Apart from the previous study delineating that LYPLAL1-DT exerted protective effects to human umbilical vein endothelial cells (HUVECs) in type 2 diabetes with macrovascular complication via mediation of the miR-204-5p/SIRT1 axis, LYPLAL1-DT has not hitherto been explored in cancers." (PMID 38111678, 2023). "SIRT1, 3, 4, 6, 7, and NAD+ may all have a role in type 2 diabetes protection." (PMID 36361416, 2022). "In summary, the data indicate that SIRT1 expression in peripheral blood mononuclear cells is significantly correlated with inflammatory cytokines levels in patients with coronary artery disease and type 2 diabetes but not with the severity of coronary lesions." (PMID 27123454, 2016).
type 2 diabetes (continued). "However, SIRT1 expression in peripheral blood mononuclear cells correlates strongly with inflammatory cytokine levels in individuals with coronary artery disease and type 2 diabetes, but not with the severity of coronary lesions." (PMID 39406930, 2024). "This newly identified SIRT1-activating property of SIL may have enormous therapeutic implications and benefits in reducing not only the myocardial I-R injury, but also other types of cardiovascular disorders related to aging and metabolic dysregulation such as Type 2 diabetes." (PMID 24466304, 2014). "The data from Li's group indicated that SIRT1 expression in peripheral blood mononuclear cells was significantly correlated with inflammatory cytokine levels in patients with CAD and type 2 diabetes but not with the severity of coronary lesions." (PMID 35224092, 2022). "High-fat-diet-fed streptozotocin-induced type 2 diabetic rats were exposed to GYY4137, a slow-releasing H2S donor with or without administration of EX527 (a SIRT1 inhibitor), and then subjected to a surgical model of IR injury of the lung." (PMID 32695008, 2020). "Our trial showed that 3 g of cinnamon supplementation for 8 weeks had no beneficial impacts on plasma levels of NF-kB, SIRT1 and systemic inflammation factors including hs-CRP, IL-6 and TNF-α in type 2 diabetic patients." (PMID 31901246, 2020). "This study elucidated that cinnamon supplementation has no beneficial effects in reduction of NF-kB, SIRT1, hs-CRP, IL-6 and TNF-α levels in type 2 diabetes patients which have a considerable role in development of atherogenesis." (PMID 31901246, 2020). "As a result, our study elucidated that the cinnamon supplementation in the way of three grams per day for 8 weeks has not remarkable effect in reduction of NF-kB, SIRT1, hs-CRP, IL-6 and TNF-α plasma levels which have key role in atherogenicity in type 2 diabetes patients." (PMID 31901246, 2020). "This randomised double-blinded cross-over study demonstrated for the first time that the oral SIRT1 activator, SRT2104, may improve arterial compliance in otherwise healthy cigarette smokers and in people with type 2 diabetes, without affecting resting measures of blood pressure." (PMID 27239324, 2016).
atherosclerosis (225 papers, 2010 to 2026). A disease characterized by the build-up of fatty material and calcium deposition in the arterial wall resulting in partial or complete occlusion of the arterial lumen. "The La Ribonucleoprotein Domain Family Member 7 (Larp7), a protein that promotes senescence by decreasing SIRT1 function, led to the development of atherosclerosis in ApoE-deficient mice when subjected to a high-fat diet." (PMID 41567643, 2025). "APS and SIRT-1-targeted drugs have great potential for the treatment of aging-associated atherosclerosis and cardiovascular disease." (PMID 38331805, 2024). "In our previous study, we discovered that suppressing Larp7 accelerates senescence by inhibiting Sirt1 activity, resulting in increased atherosclerosis in high‐fat diet (HFD) fed and ApoE deficient (ApoEKO) mice." (PMID 38818612, 2024). "SIRT1 deficiency has been reported to induce cell senescence and accelerate the progression of cardiovascular disease, particularly atherosclerosis." (PMID 38202844, 2024). "Our previous studies have established Larp7 as a new activator of Sirt1, and the reduced Sirt1 activity has been implicated in atherosclerosis." (PMID 38818612, 2024). "The data we presented in the study indicate that the miR-9-mediated SIRT1/NF-κB pathway plays a pivotal role in M1 macrophage polarization and is one of the molecular mechanisms underlying the anti-atherosclerosis effects of DMY." (PMID 37234960, 2023). "On the contrary, SIRT1 deficiency leads to increased oxidative stress, inflammation, apoptosis and autophagy, promoting blood vessels aging and atherosclerosis." (PMID 37193033, 2023). "Previous study showed that SIRT1 deficiency participated in inflammation, oxidative stress, autophagy and impaired nitric oxide production, thereby promoting atherosclerosis and I/R." (PMID 37193033, 2023). "Our study revealed that in patients with β-TM, an increment in FOXO1 and HSP72 signaling with low levels of SIRT1 is linked to accelerated atherosclerosis, which is crucial as a novel biomarker for the prediction of atherosclerosis." (PMID 36289866, 2022). "SIRT1 deficiency enhances oxidative stress, inflammation, foam cell production, and atherosclerosis progression in endothelial cells." (PMID 35607519, 2022). "SIRT1 is considered to be an anti-aging molecule involved in the regulation of senescence-associated calcification, atherosclerosis, fibrous cap stability and medial degeneration." (PMID 34977164, 2021). "Further studies showed that the expression of proteins related to PI3K/ AKT /mTOR signaling pathway in SIRT1 knockout macrophages was significantly increased, thereby inhibiting macrophage autophagy and eventually causing the formation of atherosclerosis." (PMID 34928817, 2021). "After the first report showing that SIRT1 activates eNOS, several studies using mutated rats showed that SIRT1 has protective effects against atherosclerosis." (PMID 34670596, 2021). "SIRT1 is a member of the NAD + -dependent deacetylases, and SIRT1 deficiency in endothelial cells promotes oxidative stress, inflammation, foam cell formation, and increased progression of atherosclerosis." (PMID 31146723, 2019). "In aging arteries, downregulation of Sirt1 expression contributes to the formation of plaque and foam cells, which are related with atherosclerosis when endothelium is predisposed to attack." (PMID 28546854, 2017). "Previous results indicated that RSV suppressed atherosclerosis in hypercholesterolemic rabbits and endothelium-specific overexpression of Sirt1 decreased atherosclerosis in apolipoprotein E-deficient (apoE−/−) mice." (PMID 24378473, 2014). "Overexpression of endothelial SIRT1 in apoE-deficient mice prevents the formation of atherosclerosis by improving vascular function." (PMID 23551392, 2013).
atherosclerosis (continued). "Because inhibition of SIRT1 is causally implicated in endothelial cell apoptosis in the atherosclerosis-prone aortic arch of high-fat diet-induced insulin resistant mice, expression and activity of SIRT1 were assessed in the aorta of atherosclerotic pigs." (PMID 23825667, 2013). "Silencing of SIRT1 enhances production of endothelialsuperoxide Common risk factors predisposing to atherosclerosis,such as hypercholesterolemia or aging, are associated with oxidant stress atleast in part due to an increased production of ROS." (PMID 20606253, 2010). "It is observed that in atherosclerosis there is a reduced expression of SIRT1 in VSMCs, and this deficiency is associated with increased oxidative stress processes and oxidized low-density lipoprotein (oxLDL), which in turn leads to DNA damage in vascular tissues." (PMID 41228388, 2025). "The subsequent decade (2010–2018) brought critical insights into histone modifications, with the identification of HDAC9 as a genetic risk factor for atherosclerosis and the recognition of Sirtuin 1 (silent mating type information regulation 2 homolog 1, SIRT1)." (PMID 40428388, 2025). "Exogenous supplementation with 17β-estradiol restored SIRT1 expression and slowed vascular aging in mice, indicating that SIRT1 plays a crucial role in estrogen, protecting arteries from aging and atherosclerosis, thereby reducing the risk factors for HFpEF development." (PMID 39062982, 2024). "Decreased SIRT1 expression is closely associated with vascular aging and atherosclerosis." (PMID 39857372, 2024). "Importantly, VSMC-specific SIRT1 or TRF2 mutant mice show increased atherosclerosis progression, which is associated with increased cell senescence." (PMID 38202844, 2024). "SIRT1 may exert protective effects in atherosclerosis, which is said to be a major cause of cardiovascular diseases." (PMID 38038821, 2023). "Furthermore, a reduction in aortic SIRT1 expression is consistent in individuals with a high-fat diet and is a risk factor for atherosclerosis." (PMID 32082101, 2020). "Therefore, the activation of Sirt1 in endothelial cells, monocytes/macrophages and VSMCs should be considered as a novel therapeutic target to prevent atherosclerosis associated with vascular aging." (PMID 27744418, 2016). "Thus, accumulating data supports an overall protective effect of SIRT1 activation on the chronic inflammation associated with atherosclerosis." (PMID 26904696, 2016). "Considering that increased levels of plasma PAI-1 might be an important risk factor for atherosclerosis, we hypothesized that SIRT1 is inversely correlated with PAI-1 expression in atherosclerosis." (PMID 25040736, 2014). "Taking into consideration that atherosclerosis is an aspect of the aging process we hypothesized that genetic polymorphisms at SIRT1 and FOXO1 may also play a role in carotid atherosclerosis." (PMID 25273948, 2014). "The relationshipbetween SIRT1-eNOS signaling and atherosclerosis has been implicated recentlyby Chen and colleagues, who show that SIRT1 level is higher in descendingthoracic aortas (atherosclerotic resistant region) than aortic arches(atherosclerotic prone region) of C57BL6 mice." (PMID 20606250, 2010). "Moreover, animal experiments have also shown that decreased SIRT-1 expression in blood vessels of aged mice is associated with age-related atherosclerosis of the great arteries, and age-related aortic stiffness was attenuated in mice with lifelong SIRT-1 overexpression." (PMID 37196119, 2023). "Sirt1 deficiency in endothelial cells (ECs), vascular smooth muscle cells (VSMCs) and monocytes/macrophages contributes to increased oxidative stress, inflammation, foam cell formation, senescences impaired nitric oxide production and autophagy, thereby promoting vascular aging and atherosclerosis." (PMID 27744418, 2016).
atherosclerosis (continued). "Considering that the control groupconsisted of coronary artery bypass patients affected by systemic atherosclerosis,SIRT1 levels were observed to be low in vascular aging and atherosclerosis,consistent with the literature." (PMID 41259217, 2026). "SIRT1 exerts protective effects against inflammation, vascular aging, atherosclerosis, and heart disease." (PMID 41614930, 2026). "Long non-coding RNA (lincRNA) p21 is involved in the development of atherosclerosis, and competitively binds to miR-221 to promote the deacetylation of Pcsk9 by SIRT1, thereby reducing the progression of atherosclerosis." (PMID 40710369, 2025). "In many CVDs the expression of SIRT1 was downregulated, such as hypertension, atherosclerosis, aortic aneurysm, hyperglycemia, and after ischemia/reperfusion (I/R) injury." (PMID 41011644, 2025). "Another important lncRNA is lincRNA-p21, which acts as a molecular sponge for miR-221 to induce de-acetylation of the PCSK9 promoter sequence through SIRT1, thereby inhibiting atherosclerosis development." (PMID 40764605, 2025). "SIRT1 is considered a crucial regulator of oxidative stress and has been shown to play a role in modulating CVDs, including atherosclerosis, myocardial infarction and heart failure." (PMID 41300435, 2025). "It affected vascular senescence and atherosclerosis by activating SIRT1, deacetylating FOXO3a, and modulating PGC1α." (PMID 41567643, 2025). "The stimulation of eNOS therefore promotes the production of NO, which in turn favors the upregulation of SIRT1, thus suggesting the existence of the eNOS/NO/SIRT1 axis involved in the protection of the endothelium and as a result of atherosclerosis." (PMID 41228388, 2025). "A growing number of clinical trials on sirtuin- and NAD+-boosting therapies report beneficial effects on arterial stiffening, atherosclerosis and coronary artery disease, underscoring the translational potential of Sirt1/Nrf2-targeting interventions." (PMID 40355758, 2025). "Gut microbiota‐derived metabolite TMAO aggravates atherosclerosis by inhibiting SIRT1, leading to the downregulation of SM22α and promoting smooth muscle cell inflammation via the NF‐κB pathway." (PMID 40486531, 2025). "So, despite encouraging these supportive findings about the potential role of natural SIRT1 activators as complementary strategies in the prevention and management of atherosclerosis, further studies are warranted." (PMID 41228388, 2025). "SIRT1, by inactivating p66Shc, plays a protective role against age-related endothelial dysfunction, and, consequently, atherosclerosis." (PMID 41228388, 2025). "Recent investigations focus on the therapeutic potential of SIRT1 for atherosclerosis, vascular aging, inflammation, and glucose metabolism disorder." (PMID 41567643, 2025). "In aggregate, these data indicate that rmSIRT1 delivery restores systemic SIRT1 levels and blunts molecular signatures of atherosclerosis thereby promoting atheroprotective effects in ApoE−/− mice." (PMID 40653676, 2025). "Araloside C lessened atherosclerosis by modulating macrophage polarization in RAW264.7 macrophages via Sirt1-mediated autophagy." (PMID 40864816, 2025). "The decrease in SRTI1 values in patients with APS when compared to the control group suggests SIRT1 protection in atherosclerosis patients." (PMID 40507709, 2025).